CXCR4 (C-X-C motif chemokine receptor 4)
Diseases named in the same sentence as CXCR4 in open-access papers (continued):
Sharing a sentence is not in itself a finding about the gene and the disease.
cancer (continued). "Duct-like organoid colonies with extensive stroma mimicking the topology of PDAC, SOX2 and KLF4 transcriptional factors, cancer stem cells’ functionality (CD133 +/CXCR4+ PDAC cells)." (PMID 38791452, 2024). "This is currently being tested in several CXCR4-overexpressing cancer types, and preclinical results are encouraging." (PMID 38893721, 2024). "Nonetheless, ACC is a rare cancer, making data pooling of multiple study sites indispensable to further evaluate the clinical benefit of CXCR4-directed imaging in this patient population." (PMID 38896128, 2024). "Our data characterized the ferroptosis-dependent immunosuppression energized by intratumoral CXCR4 expression neutrophils and suggest a potential cell target for cancer immunotherapies." (PMID 38487536, 2024). "Several small molecules, peptides, neutralizing antibodies, as well as antibody–drug conjugates are being tested for their efficacy in antagonizing CXCR4 function in different cancers." (PMID 39125877, 2024). "Since CXCL12-CXCR4 is the most overexpressed pathway in various cancers, several small molecule drugs and peptide inhibitors targeting CXCR4 have also been developed." (PMID 39003350, 2024). "BL8040, which is a CXCR4 antagonist, is being evaluated in clinical trials as a potential therapy for cancer." (PMID 38256077, 2024). "The CXCL12/HMGB1 heterocomplex enhances, via CXCR4, the directional migration and invasiveness of cancer cells characterized by high metastatic potential that possess a fully active thioredoxin system, contributing to maintain red-HMGB1." (PMID 38803493, 2024). "Current research indicates that alkaloids exert their anticancer effects by reducing cancer cell migration and invasion through mechanisms such as downregulating the expression of CXCR4, MMP-9, and MMP-2, or inhibiting the CXCL12-CXCR4 and CCL21-CCR7 axes." (PMID 39206194, 2024). "CXCR4 is a G-protein-coupled seven-transmembrane receptor on the cancer cell and is highly expressed in MSCs within the bone marrow, enabling MSCs to migrate to CXCR4 ligands at injured sites." (PMID 38399342, 2024). "These receptors, such as ACKR3, CXCR4, CXCR3, play a crucial role in the regulation of the immune system, are associated with inflammatory diseases and cancer, and are seen as promising drug targets." (PMID 38732237, 2024). "Drugs targeting CXCR4 are used in clinical practice for various settings, including human immunodeficiency virus and the mobilization of hematopoietic stem cells for transplantation; however, there has been a renewed focus on the targeting of CXCR4 in cancer." (PMID 38612911, 2024). "It has been shown in preclinical and early clinical studies that blocking CXCR4 can disrupt the interaction between cancer cells and the microenvironment, preventing cancer cells from migrating to secondary sites." (PMID 39070795, 2024). "The presence of metastases drastically worsens cancer prognosis and CXCR4 is closely related to this phenomenon in various solid tumors." (PMID 38791878, 2024). "C-X-C motif chemokine receptor 4 (CXCR4) is an attractive target for the diagnosis and treatment of cancers." (PMID 39431004, 2024). "Cancer-related genes such as CXCR4, MMP7, CDC20 and CDK6, and unfolded protein response (UPR)-related genes such as ATF3, ATF4, XBP1 and CHOP, showed significant differences in expression in the indicated cells." (PMID 38263248, 2024). "The CXCL12/CXCR4 axis plays a role in T cell infiltration and intratumoral trafficking in many cancer types." (PMID 38786066, 2024). "Plerixafor is a first generation CXCR4 inhibitor and is the most studied and widely used CXCR4 inhibitor, with significant evidence establishing its efficacy as an anti-cancer agent in many cancer types." (PMID 38612911, 2024). "In our analysis of CRC patients with liver metastases, CXCR4 immunohistochemical staining revealed a notable finding: the nuclei of the metastatic cancer cells displayed a pronounced positivity for CXCR4." (PMID 39195225, 2024).
cancer (continued). "Targeting CXCR4 with R54 reverts CXCL12-induced cancer cell growth in presence of CDDP/PTX, particularly in OVCAR8 and IGROV1 treated with PTX potentiating the effect of chemotherapeutic agents." (PMID 39700131, 2024). "CXCR4 is expressed in a variety of epithelial cancer cells, and modulates the proliferation, survival, and migration of cancer cells." (PMID 38221932, 2024). "Bufalin was found to inhibit the expression of CCR9, CCR10, CXCR4, and pIgR proteins, thereby suppressing IgA production and impeding cancer cell proliferation and migration." (PMID 39206194, 2024). "As we unravel the intricacies of the immune system and its components, the CXCL12/CXCR4 axis emerges as an essential player, suggesting potential therapeutic targets for several immune-related disorders such as ADs and cancers." (PMID 39070795, 2024). "In a mouse model of PDAC, administering the CXCR4 inhibitor AMD3100 (plerixafor) led to the accumulation of T cells among cancer cells, resulting in a synergistic tumoricidal effect when combined with anti-PD-L1 immunotherapy." (PMID 38835055, 2024). "The CXC-chemokine receptor-4 (CXCR4) pathway plays a role in cancer cell homing and metastasis, representing a potential target for cancer therapy, i.e., CXCR4 activates mTOR and the Bruton tyrosine kinase." (PMID 39411551, 2024). "Targeting CXCL12 binding, and subsequent CXCR4 receptor activation, is the key step in developing potent CXCR4 inhibition agents for cancer therapy." (PMID 38439632, 2024). "Fucoxanthin from brown seaweed has been shown to decrease chemokine receptor-4 (CXCR4), which is responsible for the migration, invasion, and adherence of cancer cells to endothelial cells, inhibiting in vivo metastases." (PMID 38674913, 2024). "The recent literature reported an increased level of the chemokine SDF-1 and its receptor in patients with colon cancers, and the SDF-1/CXCR4 axis is considered a valuable marker of cancer metastasis." (PMID 39195225, 2024). "Conclusively, targeting the SDF-1/CXCR4 signaling pathway represents a promising strategy in the evolving landscape of cancer immunotherapy." (PMID 39195225, 2024). "Its ligand CXCL12 is abundant in organs such as the liver, lymph nodes, and bone, and CXCR4 activation leads to the migration of cancer cells toward these organs, leading to metastasis in these areas." (PMID 39001265, 2024). "Since the CXCL12/CXCR4 axis plays a crucial role in cancer and AD pathogenesis, inhibiting it seems like a promising therapeutic approach." (PMID 39070795, 2024). "CXCR4 is expressed in liver cells (HSCs and LSECs) and in cancer cells where correlates to HCC worse prognosis." (PMID 37142825, 2024). "It has been shown to block the migration of CLL cells when CXCR4 is activated, induce apoptosis, and decrease the development and migration of cancer cells." (PMID 39198407, 2024). "Accordingly, understanding the complicated mechanisms underlying tumorigenesis, progression, and the role of the CXCL12/CXCR4 axis in these processes is essential for emerging targeted therapeutic interventions in cancer therapy." (PMID 39070795, 2024). "The first recruited motile streaming TAMs differentiate into CXCR4-expressing macrophages in a TGF-β-dependent manner and cooperate with CXCL12-expressing cancer-associated fibroblasts in the perivascular niche to promote cancer cell intravasation." (PMID 39516356, 2024). "CXCR4 and its ligand, CXCL12, are immunohistochemically overexpressed in gastric cancer compared with normal gastric tissue and are associated with cancer cell survival, proliferation, angiogenesis, and migration." (PMID 39003350, 2024). "The CXCL12/CXCR4 pathway in cancer promotes metastasis but the molecular details of how this pathway cross-talks with oncogenes are understudied." (PMID 39766093, 2024).
cancer (continued). "CXCR7 agonists can be alternative choices but with the diverse roles of CXCR7 have been reported, ranging from compensating for CXCR4 inhibitors, promoting cancer progression, treatment failure, and to counteracting CXCL12 function." (PMID 38898023, 2024). "The CXC Chemokine Receptor type 4 (CXCR4) has been demonstrated to play a pivotal role in the chemotactic invasion of cancer cells to secondary metastatic sites." (PMID 39795985, 2024). "The expression of SDF1 and CXCR4 in the skeletal muscle of individuals with cancer exhibits an inverse correlation with the expression of MURF1 and Atrogin-1." (PMID 38334644, 2024). "The FAP+CAFs were discovered to utilize the CXCR4/CXCL-12 axis to effectively exclude CD8+ T cells from the region containing cancer cells by releasing CXCL-12, ultimately preventing the CD8+ T cells from reaching the TME." (PMID 39609700, 2024). "Accordingly, ICB therapy can be applied to previously ICB-insensitive cancer types by delivering CXCR4 inhibitors liposomal to activate the immune system." (PMID 39070795, 2024). "Studies in mice have shown that CXCR4 blockade inhibits cancer cell dissemination and metastasis in several cancer models." (PMID 39035006, 2024). "The main objective of this study was to explore the potential application of the 18F-labeled CXCR4 tracer ([18F]AlF-NOTA-QHY-04) for cancer imaging." (PMID 39431004, 2024). "We further examined angiogenesis activities in each cancer type, observing that the prominent angiogenesis potential of E02-tip-CXCR4 was conserved in almost all analyzed cancers." (PMID 39345334, 2024). "The CXCL12/CXCR4 axis, significant in bone metastasis regulation, has inhibitors in clinical trials showing potential to reduce cancer cell proliferation and migration." (PMID 38474093, 2024). "Numerous studies employed CXCR4 inhibitors to suppress the CXCL12/CXCR4 signals for treating cancer." (PMID 39070795, 2024). "Targeting CXCR4 and its secondary location in tumor development is one of the major processes in the spread of cancer." (PMID 39407172, 2024). "Chemokine receptor antagonist (CRA) drugs such as plerixafor (CXCR4 antagonist) or maraviroc (CCR5 antagonist) have been shown to induce suppression of cancer cell proliferation, migration, and metastasis." (PMID 39001456, 2024). "PLGA NPs coated with cell membranes from U87‐CXCR4 (a U87 cell line stably transfected with human CXCR4) disrupted the migration of cancer cells toward fibroblasts and significantly reduced metastatic burden." (PMID 39217459, 2024). "The impact of the CXCL12/CXCR4 axis on promoting GBM growth has spurred the development of effective CXCR4 antagonists as potential anti-cancer drugs." (PMID 39162901, 2024). "Activation of the CXCL12/CXCR4 biological axis plays an essential role in the pathophysiology of several cancer types, including progression, recurrence, and metastasis." (PMID 38594611, 2024). "Different ligand–receptor pairs (such as CXCL12-ACKR3/CXCR4) play roles in both pro- and anti-tumor functions in cancer, affecting processes like angiogenesis, proliferation, differentiation, and metastasis." (PMID 38732237, 2024). "Addressing these limitations in future studies will provide a more comprehensive understanding of the role of SDF-1/CXCR4 signaling in cancer progression and its potential as a therapeutic target." (PMID 39195225, 2024). "The chemokine receptor CXCR4 is a critical target forthe treatmentof several cancer types and HIV-1 infections." (PMID 38647430, 2024). "Additional research shows that CXCR4 is overexpressed in cancer stem cells in various tumors, driving a more tumorigenic phenotype." (PMID 38893721, 2024). "The role of this molecule in the pathogenesis of MM is probably based on promoting the migration and invasion of cancer cells through inhibition of CXCR4." (PMID 38473390, 2024). "A strategy to impede cancer progression and improve treatment outcomes is effective in early clinical studies targeting CXCR4." (PMID 39070795, 2024).
cancer (continued). "Typically, CXCR4 is known for its involvement in cell signaling pathways that influence cell migration and invasion, particularly in the context of cancer metastasis." (PMID 39195225, 2024). "The CXCL12/CXCR4 axis plays an important role in various aspects of cancer biology, including angiogenesis and metastasis." (PMID 39641645, 2024). "Here the authors propose a CXCR4-targeted strategy based on interactable polymer nanothreads, showing inhibition of metastasis in preclinical cancer models." (PMID 38553476, 2024). "It is shown that stiffening of PA‐E3Yh hydrogels to levels found in PDAC induces ECM deposition, promotes epithelial‐to‐mesenchymal transition (EMT), enriches CD133+/CXCR4+ cancer stem cells (CSCs), and subsequently enhances drug resistance." (PMID 38471128, 2024). "mRNA levels of CXCR4 were more highly expressed in B-ALL than in most other human cancers (ranked 3 of 40)." (PMID 38811530, 2024). "Most studies show that nuclear, cytoplasmic, or membrane CXCR4 expression correlates with poor survival, and that CXCR4 location differs by cancer type." (PMID 38893721, 2024). "CXCR4 has been reported to be overexpressed in more than 23 different human cancers including non-small cell lung, breast, ovarian, prostate, pancreatic, and colorectal cancer." (PMID 39204345, 2024). "Our computational approach involving GNM, RIN, and SILCS wasapplied to the CXCR4 monomer and homodimer structures that are crucialtargets in cancer and HIV infection." (PMID 38647430, 2024). "Differences in CXCR4 activity and localization across various cancers suggest that additional research is necessary in order to understand the broader implications of our findings." (PMID 39195225, 2024). "CXCL12/CXCR4 is a key signaling pathway that recruits TAMs, and the blockade of the CXCL12/CXCR4 possesses great potential for cancer treatment." (PMID 38787372, 2024). "Other anti-CXCR4 antibodies such as PF-06747143 have demonstrated reduced cancer burden and migration and synergized with standard-of-care chemotherapies in preclinical models of hematological malignancies." (PMID 38612911, 2024). "CXCR4/CXCL12 axis is a promising therapeutic target for blocking the CXCL12/CXCR4 interaction and inhibiting downstream intracellular signaling for the treatment of various cancers." (PMID 39001265, 2024). "By activating the CXCL12/CXCR4 axis, cancer stem, and progenitor cells are mobilized to pre-metastatic niches and undergo epithelial-mesenchymal transition (EMT)." (PMID 39070795, 2024). "The CXCL12/CXCR4 axis plays a critical role in promoting cancer cell proliferation, migration, invasion, angiogenesis and metastasis." (PMID 39195299, 2024). "CXCR4 plays a significant role in a number of illnesses, such as cancer, autoimmune disorders, and immunodeficiency conditions." (PMID 39407172, 2024). "Beyond the CXCL12/CXCR4 axis’s physiological functions, its dysregulation concerns several pathological conditions, including cancer metastasis, ADs, and human immunodeficiency virus (HIV) infection." (PMID 39070795, 2024). "The hyperactivation of CXCL12/CXCR4 in cancer cells compared to their normal counterparts makes this axis a promising target for targeted therapy of cancer cells." (PMID 37966614, 2023). "LPA or alkyl-OMPT inhibited CXCL12-induced migration in various cancer cells that endogenously express both CXCR4 and LPA1." (PMID 37749552, 2023). "The therapeutic targeting of CXCR4 by triptolide holds significant promise in the realm of cancer treatment." (PMID 38045808, 2023). "The KR-induced autophagic phenotype in cancer cells was inhibited by treatment with the CXCR4 inhibitor AMD3100 and rapamycin." (PMID 37760498, 2023). "Another interesting finding was the differential expression of the Cxcr4 gene, coding for C-X-C Motif Chemokine Receptor 4, responsible for angiogenesis and metastasis of cancer as well as the intestinal epithelial barrier maturation and restitution." (PMID 37795356, 2023).
cancer (continued). "In recent times, an increasing number of CXCR4 inhibitors have entered clinical trials, demonstrating their pivotal role in treating patients unresponsive to checkpoint inhibitors, or those with cancer metastasis or recurrence." (PMID 38129870, 2023). "The C–X–Cchemokine receptor type 4, or CXCR4, isa chemokine receptor found to promote cancer progression and metastasisof various cancer cell types." (PMID 36944083, 2023). "In endometrial carcinoma, CAFs promote cancer progression via the SDF-1α/CXCR4 axis, through PI3K/AKT and MAPK/ERK signaling in a paracrine-dependent manner, and increase MMP-2 and MMP-9 secretion in an autocrine-dependent manner." (PMID 37046676, 2023). "The CXCR4 is a chemokine receptor overexpressed in several types of cancers and serves as a key predictor of poor overall survival in cancer patients." (PMID 37996444, 2023). "Deletion of LPAR1 in MDA-MB-231 cells increased CXCL12-induced calcium flux and cell migration, indicating that LPA1 can inhibit CXCR4 in cancer cells expressing both receptors." (PMID 37749552, 2023). "Further analyzing transcriptomic data exhibited significantly positive Pearson correlation coefficients for most cancer entities between CXCR4 and the T cell co-receptors CD4 and CD8A, as well as IRF1 and CTLA4." (PMID 36672341, 2023). "If CXCL12 binds to CXCR4 expressed by DCs, the immune trafficking processes are triggered, but if it binds to CXCR4 present on cancer cells, the LN metastasis cascade begins." (PMID 37744339, 2023). "In cancer, the co-expression of CXCR4 and Nrf2 has been related to metastasis and a poor prognosis, suggesting that an aberrant Nrf2 and CXCR4 cross-talk can be detrimental." (PMID 37240121, 2023). "Costimulation of CXCR4 and HRH1 synergistically increases calcium flux and CXCL12-induced cell migration in various cancer cells that express CXCR4 and HRH1 endogenously." (PMID 36732336, 2023). "The CXCR4 also plays a role in the accumulation and regulation of ROS levels in cancer cells, protecting cells against cellular damage from oxidative stress." (PMID 38655233, 2023). "A known CXCR4 inhibitor, CTCE‐9908 is derived from human CXCL1271, 72 and has been shown to reduce metastasis in eight different murine cancer models through CXCR4 inhibition." (PMID 37170733, 2023). "Tissues that constitutively express CXCL12 are the main sites of metastasis for CXCR4-expressing cancer cells." (PMID 36614308, 2023). "In fact, the CXCL12/CXCR4 axis is among the most studied chemokine axes in cancer metastasis due to its capacity to support cancer cell proliferation, migration and invasion." (PMID 37198402, 2023). "Based on the role of the CXCL12-CXCR4 axis in cancer metastasis, many CXCR4 antagonists for cancer therapy are in clinical development." (PMID 37198402, 2023). "CXCR4, which holds prognostic significance for various cancers, is the most commonly found of all chemokine receptors in malignant tumours." (PMID 38137380, 2023). "Beyond CD8+ T cell infiltration, CXCR4 expression significantly correlated with B cell as well as monocyte and macrophage tissue infiltration in the majority of cancer entities investigated." (PMID 36672341, 2023). "Protein expression of CXCL5/CXCR2 and CXCL12/CXCR4 were decreased with KT treatment, resulting in KT inhibiting cancer cells’ secondary growth within the bone." (PMID 36674719, 2023). "In cancer, the CXCR4/CXCL12 axis is suggested to contribute to the viability of neoplastic cells, angiogenesis and metastatic activity of malignant cells." (PMID 37108193, 2023). "CXCR4, a molecule known to be upregulated in a variety of cancers, hampers cancer cell angiogenesis and metastasis." (PMID 38129870, 2023). "Multiple oncogenic signaling cascades (EGFR, CXCR4, FASN, P-gp, β-catenin, GSK-3B, STAT1, JAK2, MUC1, etc) are hallmarks of cancer cells that are associated with drug resistance, tumorigenic potential, and metastasis." (PMID 37151801, 2023).